PURB (purine rich element binding protein B)
Description:
Transcriptional regulator which can act as an activator or a repressor. Represses the transcription of ACTA2 in fibroblasts and smooth muscle cells via its ability to interact with the purine-rich strand of a MCAT-containing element in the 5' flanking region of the gene. Represses the transcription of MYOCD, capable of repressing all isoforms of MYOCD but the magnitude of the repressive effects is most notable for the SMC-specific isoforms. Promotes hepatic glucose production by activating the transcription of ADCY6, leading to cAMP accumulation, increased PKA activity, CREB activation, and increased transcription of PCK1 and G6PC genes (By similarity). Has capacity to bind repeated elements in single-stranded DNA such as the purine-rich single strand of the PUR element located upstream of the MYC gene. Participates in transcriptional and translational regulation of alpha-MHC expression in cardiac myocytes by binding to the purine-rich negative regulatory (PNR) element Modulates constitutive liver galectin-3 gene transcription by binding to its promoter. May play a role in the dendritic transport of a subset of mRNAs (By similarity).
Synonyms: PURBETA
Tractability: PROTAC: ubiquitination databases record sites on it; its protein half-life has been measured.
Target class: Transcription factor
Gene: Protein-coding gene on chromosome 7 (44,876,299 to 44,885,530, reverse strand). Ensembl gene ENSG00000146676.
Subcellular location: Nucleus
Subcellular location (Human Protein Atlas): Nucleoplasm
Gene Ontology:
Molecular function: protein binding; RNA binding; DNA-binding transcription factor activity, RNA polymerase II-specific; DNA-binding transcription factor binding; DNA-binding transcription repressor activity, RNA polymerase II-specific; mRNA binding; mRNA regulatory element binding translation repressor activity; purine-rich negative regulatory element binding; RNA polymerase II transcription regulatory region sequence-specific DNA binding; single-stranded DNA binding; DNA-binding transcription factor activity; double-stranded DNA binding; SMAD binding
Biological process: negative regulation of transcription by RNA polymerase II; positive regulation of transcription by RNA polymerase II; regulation of myeloid cell differentiation; regulation of transcription by RNA polymerase II; negative regulation of translation
Cellular component: nucleoplasm; nucleus
Genetic constraint (gnomAD): Loss-of-function variants: 11 observed, 14.89 expected, observed/expected ratio (o/e) 0.74, 90% interval 0.46 to 1.22. The synonymous counts are far from expectation, so gnomAD's model fits this gene poorly and the ratio says little. Missense variants: 349 observed, 377.73 expected, observed/expected ratio (o/e) 0.92, 90% interval 0.85 to 1.01. Synonymous variants: 244 observed, 183.94 expected, observed/expected ratio (o/e) 1.33, 90% interval 1.19 to 1.48.
Homologues: Orthologues: chimpanzee PURB (99% identical), macaque PURB (99% identical), rat Purb (98% identical), mouse Purb (98% identical), pig PURB (96% identical), guinea pig PURB (94% identical), tropical clawed frog purb (83% identical), zebrafish purba (81% identical), zebrafish purbb (81% identical), Drosophila melanogaster Pur-alpha (39% identical), Caenorhabditis elegans plp-1 (27% identical), Caenorhabditis elegans plp-2 (15% identical). Paralogues in human: PURA (68% identical), PURG (54% identical).
Diseases named in the same sentence as PURB in open-access papers:
PURB is named in the same sentence as 14 diseases in open-access papers, as found by Europe PMC text mining. Sharing a sentence is not in itself a finding about the gene and the disease. The quoted sentences say what the papers report.
breast cancer (3 papers, 2020 to 2023). A primary or metastatic malignant neoplasm involving the breast. "The results of ectopic overexpression or siRNA-mediated knockdown of PURB, resulting in altered expression (upregulation or downregulation, respectively) of Tns1 in 4T1 mammary cancer cells indicating a transcriptional regulatory role of PURB in this context." (PMID 33353933, 2020).
abscess (1 paper, 2019). An inflammatory process characterized by the accumulation of pus within a newly formed tissue cavity which is the result of a bacterial, fungal, or parasitic infection or the presence of a foreign body. "S. aureus purB mutants have been recently shown by our group to have reduced pathogenesis, and purA mutants were found to be attenuated in a S. aureus murine abscess study." (PMID 30766531, 2019).
demyelinating disease (1 paper, 2019). A broad group of disorders that affect the myelin sheaths that cover the neurons. "Elucidation of the upstream pathways and signals that induce CC2D1B and PURβ will be important both for understanding the molecular control of the myelination program, but also potentially for identifying strategies to promote remyelination in demyelinating disease." (PMID 31379499, 2019).
HIV-1 infection (1 paper, 2026). The type species of lentivirus and the etiologic agent of acquired immunodeficiency syndrome (AIDS). "Moreover, we show that the ivRBPs PURA and its homolog PURB control HIV-1 particle infectivity and engage with several viral proteins and key elements within HIV-1 gRNA, showcasing the importance of ivRBPs for HIV-1 infection." (PMID 41955099, 2026).
pneumonia (1 paper, 2021). An acute, acute and chronic, or chronic inflammation focally or diffusely affecting the lung parenchyma, caused by an infection in one or both of the lungs (by bacteria, viruses, fungi, or mycoplasma.). "We confirmed that five (4 of which are metabolic) mutants (purB::Tn, pdhA::Tn, SAUSA300_1231::Tn, glyA::Tn, and pyc::Tn) were significantly attenuated in the acute pneumonia model by infecting mice with individual transposon mutants." (PMID 34101490, 2021).
triple-negative breast carcinoma (1 paper, 2020). An invasive breast carcinoma which is negative for expression of estrogen receptor (ER), progesterone receptor (PR), and human epidermal growth factor receptor 2 (HER2). "Immunoprecipitation (RIP) using the PURB antibody indicated a specific interaction between PURB and LINC01271 in human triple-negative breast cancer MDA-MB-231 LM2 cells." (PMID 33353933, 2020).
tumor (8 papers, 2017 to 2024). "Among them, MaTAR25 functions by regulating the expression of the gene Tensin1 via purine-rich element binding protein B (PURB), affecting tumor proliferation, migration and invasion." (PMID 37837543, 2023). "For instance, the long noncoding mammary tumour-associated RNA25 (MaTAR25) downregulated Tensin1 (Tns1) protein in 4T1 cells by interacting with purine-rich element binding protein B (PURB) and heightened tumor cell progression." (PMID 36267139, 2022). "The Gal4-dependent upregulation of PURB (transcriptional activator protein Pur-beta) and MAPKAPK3 (MAPK-Activated Protein Kinase 3) expression, as well as the downregulation of BTF3 (Basic Transcription Factor 3) and BCAR1(Breast Cancer Anti-Estrogen Resistance Protein 1), could be confirmed." (PMID 35742860, 2022).
infection (7 papers, 2011 to 2024). The state of being infected such as from the introduction of a foreign agent such as serum, vaccine, antigenic substance or organism. "These include mutations in purA, purB, and clpX, which have been shown to be important in various models of infection (12, –, 14)." (PMID 34101490, 2021). "Mutations in two of these genes, purB and clpP, led to significantly reduced pathogenesis in a zebrafish model of infection." (PMID 30766531, 2019). "purB and clpP were subsequently found to be necessary for bacterial replication and pathogenesis in a zebrafish embryo infection model." (PMID 30766531, 2019). "Preserving neutrophil function during infection by preventing S. aureus-induced cell death is therefore an attractive therapeutic strategy and here we describe three genes (purB, clpP, and lspA) with previously unidentified roles in neutrophil cell death." (PMID 30766531, 2019). "Addition of adenine and inosine to RPMI during the infection partially restored the ability of the purB mutant to induce neutrophil cell lysis, although this was not statistically significant." (PMID 30766531, 2019). "Three genes (purA, purB, and pabA) were subsequently found to be required for pathogenesis in the zebrafish embryo infection model." (PMID 28808156, 2017). "Thus, for instance, the purB and purH gened in Mesorhizobiumi loti are involved in infection thread formation and nodule development in Lotus japonicus." (PMID 21801415, 2011). "In the presence of adenine, only the purH mutant induced nodule formation, and the purB mutant produced few infection threads, suggesting that 5-aminoimidazole-4-carboxamide ribonucleotide biosynthesis catalyzed by PurB is required for the establishment of symbiosis." (PMID 21801415, 2011). "The purB gene (GAM18), which encodes an adenylosuccinate lyase involved in the biosynthesis of purines, has been described as essential for rhizosphere colonization by Pantoea agglomerans and for infection thread formation and nodule development in Lotus japonicus induced by Mesorhizobium loti." (PMID 30478234, 2019). "Since clpP, lspA, and purB mutants were defective in causing neutrophil lysis and therefore may not overcome neutrophil defenses during infection, we hypothesized these strains would have altered pathogenicity in vivo." (PMID 30766531, 2019). "Thus, mutations in SAUSA300_1231, pyc, purB, pdhA, and glyA represent genes important for pathogenesis across all models of infection and highlight the importance of purine and glycine metabolism, γ-aminobutyrate transport, and flux into the TCA cycle during infection." (PMID 34101490, 2021). "al showed that purA and purB are essential for growth of JE2 in human and rabbit blood, and pathogenesis in a zebrafish embryo infection model." (PMID 30625152, 2019). "Biochemical complementation of the purA and purB mutants was not successful in the zebrafish infection model, likely due to poor diffusion of nucleobases into zebrafish embryos (data not shown)." (PMID 28808156, 2017).
cancer (3 papers, 2020 to 2022). A tumor composed of atypical neoplastic, often pleomorphic cells that invade other tissues. "The expression or activity of PURB is altered in several cancers." (PMID 35742860, 2022). "Future investigation of these potential interactions may provide further insights into the molecular mechanism of the MaTAR25- PURB complex in cancer cells." (PMID 33353933, 2020). "As the interaction of PURB with MaTAR25 is essential for PURB binding to Tns1 DNA this suggests that MaTAR25 acts as a chaperone and/or scaffold for the MaTAR25/PURB/Tns1 DNA complex, which is critical for transcriptional regulation of Tns1 thereby impacting cancer progression." (PMID 33353933, 2020).
hematologic malignancies (1 paper, 2022). "PURA and PURB are nucleic acid-binding proteins that form nucleoprotein complexes associated with hematologic malignancies and hyperproliferation." (PMID 35831314, 2022).
neurodegenerative disease (1 paper, 2022). A disorder of the central nervous system characterized by gradual and progressive loss of neural tissue and neurologic function. "The ‘Human UP’ genes include FOXP2, MTRNR2L8, DHX40, VPS13B, WDFY2 and PURB, all of which are associated with neurodevelopment or neurodegenerative disease." (PMID 36052683, 2022).
PURB also shares sentences with these, for which no sentence is quoted: Breast (1 paper); cholangiocarcinoma (1); myeloid malignancies (1).